SPARC (secreted protein acidic and cysteine rich)
Diseases named in the same sentence as SPARC in open-access papers (continued):
Sharing a sentence is not in itself a finding about the gene and the disease.
soft tissue sarcoma (2 papers, 2014 to 2016). A malignant neoplasm arising from muscle tissue, adipose tissue, blood vessels, fibrous tissue, or other supportive tissues excluding the bones. "In this report, we sought to evaluate SPARC expression in a more uniform population of patients with high risk soft tissue sarcoma." (PMID 27544129, 2016). "Using primary biopsy and resection specimens from patients with high-risk localized, soft tissue sarcoma treated on a neo/adjuvant chemotherapy study, SPARC expression was assessed and compared to patient and tumor characteristics, treatment, and outcomes." (PMID 27544129, 2016). "A recent large study of a varied group of 2539 bone and soft tissue sarcoma specimens evaluated SPARC expression by IHC using a cutoff of ≥ 2+ and ≥ 30 % for positivity." (PMID 27544129, 2016). "SPARC’s role, and potentially the role of NAB-paclitaxel, in the highly heterogeneous class of soft-tissue sarcomas (STS) has not been investigated." (PMID 24484617, 2014).
steatosis (2 papers, 2018 to 2023). Increased lipid within the cytoplasm of cells. "Gene ontology analysis revealed that genes positively correlated with SPARC are linked to inflammasome-related pathways during the progression of the disease, enabling the differentiation of patients between steatosis and steatohepatitis." (PMID 37834291, 2023). "In line with this, WD caused higher macrovesicular steatosis in SPARC−/− mice in comparison with SPARC+/+ mice, demonstrated by HE and Oil Red O staining." (PMID 29335425, 2018). "We previously demonstrated that after 12 weeks of Western diet feeding (WD), SPARC+/+ and SPARC−/− mice developed steatosis." (PMID 37834291, 2023). "In this study, we wondered whether SPARC might act as a DAMP-promoting inflammasome activation in the in vitro steatosis assay and in high-fat diet-induced NAFLD mice." (PMID 37834291, 2023).
subarachnoid hemorrhage (2 papers, 2025). A serious neurological disorder characterized by intracranial hemorrhage into the subarachnoid space. "A recent study demonstrated that SPARC also aggravates blood–brain-barrier disruption after subarachnoid hemorrhage via αvβ3-integrin signaling pathway-mediated endothelial cell injury." (PMID 40362650, 2025).
abdominal aortic aneurysm (1 paper, 2023). Enlargement and ballooning of the vessel that supplies arterial blood to the abdomen, pelvis and legs. "In addition, single-cell sequencing of human abdominal aortic aneurysms suggested that SPARC was highly expressed in proliferation-associated smooth muscle cells and fibroblasts." (PMID 38076208, 2023).
ameloblastoma (1 paper, 2024). The most common odontogenic tumor, arising from the epithelial component of the embryonic tooth and usually affecting the molar-ramus region of the mandible or maxilla. "In ameloblastoma, SPARC expression showed a significant correlation with MMP-9 expression, suggesting that SPARC participates in local aggressiveness of this tumor." (PMID 38347494, 2024).
anaphylaxis (1 paper, 2022). An acute hypersensitivity reaction that occurs from exposure to an allergen. "Our validation work demonstrated the downregulation of six platelet‐related genes (TLN1, GATA1, SELP, SPARC, MPL and F13A1) in anaphylaxis patients compared with healthy controls." (PMID 36583159, 2022). "Six genes (GATA1 (P‐value = 2.52 × 10−2), SELP (P‐value = 1.86 × 10−2), MPL (P‐value = 2.72 × 10−2), F13A1 (P‐value = 1.62 × 10−2), SPARC (P‐value = 2.97 × 10−2) and TLN1 (P‐value = 6.13 × 10−3)) were significantly downregulated in anaphylaxis patients compared with healthy controls." (PMID 36583159, 2022). "Seven genes (TLN1, GATA1, SELP, GP1BA, MPL, F13A1 and SPARC) were also downregulated in patients with severe anaphylaxis who did not receive adrenaline before ED arrival, compared with healthy controls." (PMID 36583159, 2022).
aneurysmal bone cyst (1 paper, 2023). A locally aggressive and destructive benign cystic lesion of the bone. "In aneurysmal bone cyst, the osteonectin gene SPARC has been identified as one of the possible fusion partners in the characteristic UPS6-rearrangement of the lesion." (PMID 37509363, 2023).
angle-closure glaucoma (1 paper, 2008). The sudden increase of intraocular pressure, resulting in pain and an abrupt decrease in visual acuity. "However, in PACG, we propose that SPARC through its effect on iris ECM composition is likely to contribute to changes in iris biomechanics that define angle closure glaucoma." (PMID 18949063, 2008).
arterial embolism (1 paper, 2025). An arterial embolism occurs when a foreign substance or tissue mass gets lodged in an artery and obstructs the blood flow. "Our study identified SPARC as a risk factor for ICH and confirmed that SPARC has the potential to increase the risk of arterial embolism." (PMID 38977622, 2025). "Additionally, SPARC increased the risk of arterial embolism (OR = 1.64; 95% CI, 1.11–2.42; Pfdr = 0.038)." (PMID 38977622, 2025). "SPARC-mediated inflammation and vessel wall damage may be responsible for the development of ICH and arterial embolism and thrombosis." (PMID 38977622, 2025).
Arthritis (1 paper, 2023). Inflammation of a joint. "The downregulation of SPARC synthesis by inflammatory cytokines, including IL-1 and TNF-α, during the acute phase of arthritis, as verified by Nakamura, further supports our hypothesis about the role of SPARC in immune function and suggests that TNF-α can modulate SPARC reversal." (PMID 37355563, 2023).
B-cell lymphoma (1 paper, 2010). "The growth of Lewis lung carcinoma and B-cell lymphoma was enhanced in mice lacking endogenous SPARC." (PMID 20087345, 2010).
Barrett adenocarcinoma (1 paper, 2003). An adenocarcinoma arising from Barrett metaplastic epithelium in the esophagus. "SPARC expression was increased even in Barrett's IM tissues, indicating that the induction of the expression of this gene is an early event in the Barrett's adenocarcinoma progression." (PMID 14562024, 2003).
Becker muscular dystrophy (1 paper, 2023). Becker muscular dystrophy (BMD) is a neuromuscular disease characterized by progressive muscle wasting and weakness due to degeneration of skeletal, smooth and cardiac muscle. "Sparc is a less known regeneration marker, but upregulation of the protein product SPARC has been shown to reflect the severity of lesions in DMD and Becker muscular dystrophy biopsies." (PMID 37582915, 2023).
bladder tumor (1 paper, 2021). "In human bladder tumor tissues, the frequency and intensity of SPARC were inversely correlated with disease-specific survival." (PMID 33388091, 2021).
bone metastasis (1 paper, 2015). Transfer of a neoplasm from its primary site to bones. "However, for bone metastasis predictive value, the association of SPARC signal with those of Endothelin 1/ETAR seemed essential, starting from their presence in the dysplastic lesions." (PMID 26703564, 2015). "Concomitantly, the expression of Endothelin 1 and of its receptor ETAR were assayed to clarify whether the Endothelin 1/ETAR pattern completed SPARC findings as predictive value for bone metastasis." (PMID 26703564, 2015). "In conclusion, without associated strong SPARC expression, the Endothelin 1/ETAR positivity in dysplastic lesions did not appear to be sufficient as predictive index of bone metastasis." (PMID 26703564, 2015).
bone sarcoma (1 paper, 2016). A sarcoma that arises from the bone. "There also were no vascular or bone sarcomas in our dataset which may be subtypes for which SPARC has higher prognostic potential." (PMID 27544129, 2016).
Cachexia (1 paper, 2023). Severe weight loss, wasting of muscle, loss of appetite, and general debility related to a chronic disease. "We found that the modulation of ECM secretion via SPARC or Rab10 can ameliorate the cachexia phenotype." (PMID 38014610, 2023).
calcification (1 paper, 2024). Process by which organic tissue becomes hardened by the physiologic deposit of calcium salts. "We showed that fibrosis, pathological gingival calcifications and increased expression of various profibrotic and pro-osteogenic proteins such as POSTN, SPARC and VIM were common findings." (PMID 38664418, 2024).
central obesity (1 paper, 2022). "Eleven types of variants in 4 genes (COL6A2, FTO, SPARC, and MTHFR) were found to be related to central obesity, and 8 of 48 subjects with MetS (16.7%) showed putative non-synonymous variants in these genes." (PMID 35999587, 2022).
cerebral aneurysms (1 paper, 2013). "We sought to determine the regulatory events associated with the expression of SPARC, MMP-2 and MMP-9 in ruptured and unruptured human cerebral aneurysms." (PMID 23516489, 2013).
choriocarcinoma (1 paper, 2013). An aggressive malignant tumor arising from trophoblastic cells. "We found that HTR8/SVneo cells had a much higher mRNA and protein expression of SPARC than JEG-3 cells, a cell line of choriocarcinoma origin." (PMID 23935929, 2013).
chronic kidney disease (1 paper, 2025). Impairment of the renal function secondary to chronic kidney damage persisting for three or more months. "These properties SPARC has of binding to collagen and calcium have been illustrated in a previous publication that proposed an explanation of the “bone mineral density protection paradox” in obese patients with chronic kidney disease." (PMID 40299645, 2025). "For instance, in our specific example of vascular calcification, for individuals with normal calcium levels, increased SPARC levels would not lead to vascular calcification seen in patients suffering from chronic kidney disease who have hypercalcemia." (PMID 40299645, 2025).
collagenopathies (1 paper, 2025). "For illustration, diseases/drugs causing variations in calcium levels (hyperparathyroidism, vitamin D intake) and collagen expression (collagenopathies) could either limit/reduce the benefits of SPARC on bones or lead to side effects such as vascular calcification." (PMID 40299645, 2025).
concussion (1 paper, 2021). A concussion, also known as a mild traumatic brain injury (mTBI), is a head injury that temporarily affects brain functioning. "Combining three of the protein biomarkers (ATOX1, SPARC and NT5C3A), produced an AUC of 0.98 for concussion diagnoses (P < 0.001; 95% CI: 0.95, 1.00)." (PMID 34987469, 2021).
craniopharyngioma (1 paper, 2021). A benign, partly cystic, epithelial tumor of the sellar region, presumably derived from Rathke pouch epithelium. "In craniopharyngioma, a higher tumor stroma expression of SPARC leads to higher brain infiltration." (PMID 34503278, 2021).
cutaneous melanoma (1 paper, 2025). A primary melanoma arising from atypical melanocytes in the skin. "Overall, these results indicate that SPARC is a key EMT gene in the progression of cutaneous melanoma." (PMID 40943659, 2025). "SPARC-centered networks were identified by GSEA on the pre-ranked genes of the Cancer Genome Atlas-Skin Cutaneous Melanoma (TCGA-SKCM) dataset." (PMID 40943659, 2025).
deafness (1 paper, 2018). An inherited or acquired condition characterized by the complete loss of the ability to hear from one or both ears. "Proteins such as SPARC and unconventional myosin-VI (Myo6), known to be associated with cochlear development, hearing, and deafness, were identified among these proteins." (PMID 30127667, 2018).
dental caries (1 paper, 2014). The decay of a tooth, in which it becomes softened, discolored, and/or porous. "Although the function of SPARC in dentin formation remains to be determined, some authors have suggested that odontoblasts release SPARC to stimulate the proliferation of a fraction of pulp cells to replace those injured cells by dental caries or by cavity preparation." (PMID 25047033, 2014).
depression (1 paper, 2013). "Furthermore, differences between MDD and BPD were seen for matrix-associated growth factors APP and SPARC, immune gene TNF, and transcription factors CREB1, NFKB1, and NR3C1 when controlling for depression severity, age, and medication use." (PMID 24143878, 2013).
diabetic retinopathy (1 paper, 2022). "In-depth transcriptomic analysis of the human retina reveals molecular mechanisms such as SPARC underlying diabetic retinopathy." (PMID 35721704, 2022). "SPARC promotes diabetic retinopathy via the regulation of integrin β1." (PMID 35721704, 2022). "However, more in-depth studies on the role of SPARC in diabetic retinopathy are currently lacking." (PMID 35721704, 2022).
dry eye (1 paper, 2024). "Using established criteria for grading dry eye severity, model dogs displaying moderate to severe clinical symptoms were selected to evaluate the therapeutic potential of ADMSC overexpressing SPARC in treating dry eye." (PMID 38956738, 2024). "This study examines the impact of ADMSC with SPARC overexpression on the treatment of benzalkonium chloride-induced dry eye in canines." (PMID 38956738, 2024). "Here, we aimed to use ADMSC overexpressing Secreted Protein Acidic and Rich in Cysteine (SPARC) to treat 0.25% benzalkonium chloride-treated dogs with dry eye to verify its efficacy." (PMID 38956738, 2024). "Furthermore, the expression of SPARC undergoes regulation during corneal repair, which is closely intertwined with the pathogenesis and progression of eye disorders like dry eye." (PMID 38956738, 2024). "Thus, the potential of using SPARC gene-modified ADMSC to treat dry eye is a significant scientific inquiry that merits investigation." (PMID 38956738, 2024). "We aimed to further ascertain the enhancing impact of SPARC on the efficacy of ADMSC at the cellular level, given that the destabilization of corneal epithelial cells stands as the focal point of dry eye pathogenesis." (PMID 38956738, 2024). "The in vitro cell test and in vivo model totally suggest that the combination of SPARC and ADMSC has a promising future in novel dry eye therapy." (PMID 38956738, 2024). "This suggests that SPARC-modified ADMSC may enhance local administration efficacy and exhibit improved therapeutic benefits for dry eye." (PMID 38956738, 2024). "This study demonstrated that SPARC-modified ADMSC showed superior efficacy compared to either ADMSC or cyclosporine eye drops alone in promoting corneal healing, up-regulating tear secretion, and suppressing periocular inflammation in a canine model of dry eye induced with 0.25% BAC." (PMID 38956738, 2024). "Overall, these results suggest that overexpression of SPARC contributes to the repair of transient membrane glands and cuprocytes, proliferation of corneal epithelial cells, and inhibition of inflammatory response, thereby promoting the efficacy of ADMSC in treating dry eye syndrome." (PMID 38956738, 2024).
endometrial tumor (1 paper, 2021). "The involvement of matricellular glycoprotein, SPARC, has been identified as a part of endometrial tumor cells affecting stromal CAFs in favor of enhancing their phenotypes." (PMID 34502029, 2021). "The study demonstrated that in the presence of fibronectin, SPARC (secreted from SPARC-expressing endometrial tumor cells) activated fibroblasts." (PMID 34502029, 2021).
epilepsy (1 paper, 2020). A brain disorder characterized by episodes of abnormally increased neuronal discharge resulting in transient episodes of sensory or motor neurological dysfunction, or psychic dysfunction. "In summary, this study found that SPARC plays a major role in nerve injury, especially epilepsy." (PMID 33584170, 2020).
experimental autoimmune encephalomyelitis (1 paper, 2016). An autoimmune demyelinating disease of the central nervous system that is produced experimentally in animals by the injection of homogenized brain or spinal cord in Freund's adjuvant. "During the peak phase of experimental autoimmune encephalomyelitis (EAE), an animal model of the chronic inflammatory demyelinating disease MS, CD31-positive blood vessels become intensely SPARC positive by immunohistochemistry (Roskams Lab, unpublished observations)." (PMID 27581191, 2016).
fatty liver (1 paper, 2023). "Despite its association with increased hepatic steatosis, SPARC−/− mice show less hepatic inflammation in later stages of the disease." (PMID 37834291, 2023). "SPARC acts as an adipogenesis inhibitor in adipose tissue, and its absence increases adipose deposits with the concomitant increase in FFA in the context of liver steatosis." (PMID 37834291, 2023).
fragile X syndrome (1 paper, 2018). A genetic syndrome caused by mutations in the FMR1 gene which is responsible for the expression of the fragile X mental retardation 1 protein. "Similarly, hevin and SPARC showed altered expression patterns in a Fragile X Syndrome (FXS) mouse model caused by a deficiency in the fragile X mental retardation protein (FMRP)." (PMID 29867379, 2018).
gastro-oesophageal reflux disease (1 paper, 2003). "SPARC mRNA expression was measured using a quantitative real-time RT–PCR method in 108 specimens from 19 patients with BE without carcinoma, 20 patients with Barrett's-associated adenocarcinoma (EA), and a control group (CG) of 10 patients without evidence of gastro-oesophageal reflux disease." (PMID 14562024, 2003).
Glucose intolerance (1 paper, 2013). Glucose intolerance (GI) can be defined as dysglycemia that comprises both prediabetes and diabetes. "SPARC may link inflammation and glucose intolerance by excessive synthesis of ECM components." (PMID 24349098, 2013).
heart failure (1 paper, 2019). Inability of the heart to pump blood at an adequate rate to meet tissue metabolic requirements. "Taken together, these data demonstrate a protective effect of SPARC on cardiomyocyte function prior to the establishment of virus-induced heart failure." (PMID 30933983, 2019).
Hepatitis (1 paper, 2013). Inflammation of the liver. "A significant reduction in the periportal or periseptal interface hepatitis, focal necrosis and portal inflammation were observed in TAA-treated SPARC−/− when compared to TAA-treated SPARC+/+ mice." (PMID 23408952, 2013).
incontinence (1 paper, 2013). "Additional prospective studies are warranted to verify these preliminary findings and compare the impact of SPARC with that of other anti-incontinence procedures." (PMID 23936860, 2013).